FABP9 (fatty acid binding protein 9)
Synonyms: TLBP; T-FABP; PERF; PERF15
Tractability: Small molecule: a structure with a bound ligand is known; it has a high-quality binding pocket.
Target class: Fatty acid binding protein family; Auxiliary transport protein
Gene: Protein-coding gene on chromosome 8 (81,458,253 to 81,461,579, reverse strand). Ensembl gene ENSG00000205186.
Subcellular location: Cytoplasm
Pathways (Reactome):
Metabolism: Triglyceride catabolism
Gene Ontology:
Molecular function: lipid transporter activity; long-chain fatty acid binding; lipid binding
Biological process: long-chain fatty acid transport; triglyceride catabolic process
Cellular component: cytosol; nucleus; perinuclear theca; cytoplasm
Genetic constraint (gnomAD): Loss-of-function variants: 6 observed, 7.78 expected, observed/expected ratio (o/e) 0.77, 90% interval 0.42 to 1.5. That is too few expected variants to judge how well the gene tolerates losing a copy. Missense variants: 121 observed, 110.73 expected, observed/expected ratio (o/e) 1.09, 90% interval 0.94 to 1.27. Synonymous variants: 38 observed, 36 expected, observed/expected ratio (o/e) 1.06, 90% interval 0.81 to 1.38.
Homologues: Orthologues: chimpanzee FABP9 (99% identical), macaque FABP9 (98% identical), rabbit PMP2 (84% identical), dog FABP9 (76% identical), pig FABP9 (76% identical), mouse Fabp9 (71% identical), rat Fabp9 (68% identical), zebrafish fabp4b (50% identical), zebrafish fabp4a (45% identical), Drosophila melanogaster fabp (39% identical), Caenorhabditis elegans lbp-7 (36% identical), Caenorhabditis elegans lbp-8 (33% identical), and 2 more. Paralogues in human: PMP2 (67% identical), FABP4 (64% identical), FABP12 (58% identical), FABP3 (55% identical), FABP7 (53% identical), FABP5 (50% identical), RBP2 (36% identical), RBP7 (36% identical), CRABP1 (36% identical), CRABP2 (35% identical), RBP1 (34% identical), RBP5 (31% identical), and 3 more.
Diseases named in the same sentence as FABP9 in open-access papers:
FABP9 is named in the same sentence as 15 diseases in open-access papers, as found by Europe PMC text mining. Sharing a sentence is not in itself a finding about the gene and the disease. The quoted sentences say what the papers report.
prostate carcinoma (3 papers, 2016 to 2025). A carcinoma that arises from epithelial cells of the prostate gland. "Since the combined GS is the most commonly used parameter to stratify the stage of prostate cancer, the fact that the increased FABP9 level is significantly associated with the increased GS suggests that FABP9 expression may be a useful prognostic factor." (PMID 27779102, 2016). "FABP9 is significantly overexpressed in malignant prostate cancer cell lines (e.g., PC-3, PC3-M) and prostate cancer tissues." (PMID 40717587, 2025). "Inhibition of FABP9 reduces the invasiveness of highly invasive prostate cancer cells (PC3-M), suggesting that it promotes tumor invasion through lipid metabolism regulation." (PMID 40717587, 2025). "Our results suggest that FABP9 is a valuable prognostic marker to predict the outcomes of prostate cancer patients, perhaps by playing an important role in prostate cancer cell invasion." (PMID 27779102, 2016). "The results also suggest that FABP9 is a valuable prognostic marker to predict the outcomes of prostate cancer patients." (PMID 27779102, 2016). "Thus the reduced level of expression of FABP9 is closely related to the reduced invasive ability of the highly-malignant prostate cancer cells." (PMID 27779102, 2016). "FABP9 is a more reliable prognostic marker than PSA to predict the outcome of prostate cancer patients and it may play an important role in the invasion of prostate cancer cells." (PMID 27779102, 2016).
breast carcinoma (2 papers, 2016 to 2025). "FABP9 is included in an immune gene-based prognostic model for breast cancer, and its high expression is significantly associated with reduced overall survival." (PMID 40717587, 2025). "FABP9 (Fatty Acid Binding Protein 9, Testis) is a Protein Coding gene which is associated with sporadic breast cancer." (PMID 26964035, 2016). "FABP9 mRNA levels are significantly higher in tumor tissues than in normal tissues, suggesting that it may promote breast cancer progression through lipid metabolism or immune microenvironment regulation." (PMID 40717587, 2025).
cardiomyopathy (1 paper, 2024). A disease of the heart muscle or myocardium proper. "FABP9 is believed to have binding affinity with long-chain fatty acids, and deficiencies in mitochondrial metabolism of long-chain fatty acids can cause elevated ROS and severe cardiomyopathy." (PMID 38207075, 2024).
hepatocellular carcinoma (1 paper, 2025). A malignant tumor that arises from hepatocytes. "In hepatocellular carcinoma (HCC), FABP9 co-amplifies with other FABP family members (e.g., FABP4, FABP5), which may synergistically promote lipid metabolic reprogramming and tumor progression." (PMID 40717587, 2025). "In hepatocellular carcinoma (HCC), FABP12 forms a gene cluster with FABP4, FABP5, FABP8, and FABP9, which is frequently co-amplified." (PMID 40717587, 2025).
liver cancer (1 paper, 2025). An epithelial or non-epithelial malignant neoplasm that arises from the liver. "FABP9 as a potential therapeutic target for tumors: Inhibiting FABP9 can reduce tumor cell invasiveness, especially in FABP9-overexpressing liver cancer, and targeted intervention may become a new strategy." (PMID 40717587, 2025).
psoriasis (1 paper, 2022). An autoimmune condition characterized by red, well-delineated plaques with silvery scales that are usually on the extensor surfaces and scalp. "Psoriasis is known to be associated with oxidative stress; hence, FABP-9 could potentially play a protective role in such patients." (PMID 36144237, 2022).
skin tumours (1 paper, 2019). "The rabbit skin tumours induced via blood infection displayed decreased expression of SLN, TAC1, MYH8, PGAM2, and APOBEC2 and increased expression of SDRC7, KRT16, S100A9, IL36G, and FABP9, as seen in tumours induced by local infections." (PMID 31340720, 2019).
type 1 diabetes mellitus (1 paper, 2021). A chronic condition characterized by minimal or absent production of insulin by the pancreas. "FABP9 was significantly correlated with “putative role of Tregs in COPD”, “breakdown of CD4+ T-cell peripheral tolerance in type 1 diabetes mellitus”, and “immune response_IL-16 signaling pathway” in the development of CRC." (PMID 34680577, 2021).
tumor (4 papers, 2019 to 2025). "Recently, studies have found that FABP9 is abnormally expressed in various cancers and is closely related to tumor progression, invasion, and patient prognosis." (PMID 40717587, 2025). "Immune regulation: In ESCC, FABP9 may affect anti-tumor immune responses by regulating CD4 + T cell infiltration." (PMID 40717587, 2025). "The mechanisms of FABP9 in cancer may include: lipid metabolism and invasion: FABP9 promotes tumor cell energy supply and membrane structure remodeling by binding to fatty acids, enhancing invasive capacity." (PMID 40717587, 2025). "Consistent with RNA-seq data, the expression of SLN, TAC1, MYH8, and PGAM2 were down-regulated, whereas SDRC7, KRT16, S100A9, IL36G, and FABP9 were up-regulated in both blood (Animal #9, #11, and #12) and skin (Animal #6, #7, and #8)-induced tumours relative to normal skin controls." (PMID 31340720, 2019). "However, mRNA expression levels of FABP1, FABP2, FABP5, FABP6, FABP7, FABP9, or FABP12 did not significantly differ in different tumor stages in CRC patients." (PMID 34680577, 2021).
cancer (3 papers, 2016 to 2025). A tumor composed of atypical neoplastic, often pleomorphic cells that invade other tissues. "In summary, FABP9 promotes cancer through lipid metabolism, immune microenvironment, and epigenetic modification, and its high expression is significantly associated with poor prognosis." (PMID 40717587, 2025). "When analysed in an archival set of human prostate tissues, immunohistochemical staining intensity for FABP9 was significantly higher in carcinomas than in benign cases and the increase in FABP9 was significantly correlated with reduced patient survival times." (PMID 27779102, 2016). "The increased level of FABP9 is significantly correlated with the increased malignancy of the carcinomas, as reflected by the increased GS." (PMID 27779102, 2016). "Mechanistic diversity: The mechanisms of FABP9 may vary across different cancers, and further research is needed on its upstream and downstream pathways and interacting proteins." (PMID 40717587, 2025). "In pan-cancer analyses, FABP8 forms a gene cluster with FABP4, FABP5, FABP9, and FABP12, which frequently undergo co-amplification in various cancers." (PMID 40717587, 2025). "Except for FABP5, mRNA levels of FABP12, FABP4, FABP9 and FABP8 were upregulated in cancers with higher Gleason scores." (PMID 33352874, 2020). "The immunohistochemical analysis showed the staining intensity of FABP9 was significantly higher in carcinomas than in BPH and the increased FABP9 stain was significantly correlated with the increased degree of malignancy, as reflected by the increased GS." (PMID 27779102, 2016). "Comparing the FABP9 expression between BPH and carcinomas, the staining intensity in carcinoma tissues was significantly stronger (χ2 test, p<0.0001)." (PMID 27779102, 2016).
infection (1 paper, 2013). The state of being infected such as from the introduction of a foreign agent such as serum, vaccine, antigenic substance or organism. "Our datas indicate that FABP9 and FABP10 are associated with responses to LPS during early infection and may also be involved in general antibacterial defensed by recognize the surface of bacteria and hemocytes in E. sinensis." (PMID 23365646, 2013).
FABP9 also shares sentences with these, for which no sentence is quoted: colorectal cancer (1 paper); esophageal squamous cell carcinoma (1); Infertility (1); influenza (1).